PSME4 (proteasome activator subunit 4)
Description:
Associated component of the proteasome that specifically recognizes acetylated histones and promotes ATP- and ubiquitin-independent degradation of core histones during spermatogenesis and DNA damage response. Recognizes and binds acetylated histones via its bromodomain-like (BRDL) region and activates the proteasome by opening the gated channel for substrate entry. Binds to the core proteasome via its C-terminus, which occupies the same binding sites as the proteasomal ATPases, opening the closed structure of the proteasome via an active gating mechanism. Component of the spermatoproteasome, a form of the proteasome specifically found in testis: binds to acetylated histones and promotes degradation of histones, thereby participating actively to the exchange of histones during spermatogenesis. Also involved in DNA damage response in somatic cells, by promoting degradation of histones following DNA double-strand breaks.
Synonyms: Blm10; hBlm10; KIAA0077; PA200
Tractability: Small molecule: a structure with a bound ligand is known. PROTAC: ubiquitination databases record sites on it; its protein half-life has been measured.
Gene: Protein-coding gene on chromosome 2 (53,864,069 to 53,971,040, reverse strand). Ensembl gene ENSG00000068878.
Subcellular location: Cytoplasm, cytosol; Nucleus; Nucleus speckle
Subcellular location (Human Protein Atlas): Nucleoplasm
Pathways (Reactome):
Metabolism of proteins: Proteasome assembly
Gene Ontology:
Molecular function: protein binding; peptidase activator activity; proteasome binding
Biological process: DNA damage response; DNA repair; flagellated sperm motility; proteasomal ubiquitin-independent protein catabolic process; sperm DNA condensation
Cellular component: nucleoplasm; nucleus; cytosol; proteasome complex; spermatoproteasome complex; nuclear speck
Genetic constraint (gnomAD): Loss-of-function variants: 67 observed, 209 expected, observed/expected ratio (o/e) 0.32, 90% interval 0.26 to 0.39. The upper end of that interval is the gene's LOEUF score, 0.39, which puts it in group 1 of 6, group 1 being the genes least tolerant of losing a copy. Missense variants: 1,765 observed, 1,998.5 expected, observed/expected ratio (o/e) 0.88, 90% interval 0.85 to 0.92. Synonymous variants: 734 observed, 697.81 expected, observed/expected ratio (o/e) 1.05, 90% interval 0.99 to 1.12.
Homologues: Orthologues: macaque PSME4 (99% identical), chimpanzee PSME4 (99% identical), dog PSME4 (97% identical), pig PSME4 (97% identical), guinea pig PSME4 (96% identical), mouse Psme4 (96% identical), rat Psme4 (96% identical), tropical clawed frog psme4 (82% identical), zebrafish psme4b (77% identical), zebrafish psme4a (74% identical), Caenorhabditis elegans C14C10.5 (31% identical).
Diseases named in the same sentence as PSME4 in open-access papers:
PSME4 is named in the same sentence as 43 diseases in open-access papers, as found by Europe PMC text mining. Sharing a sentence is not in itself a finding about the gene and the disease. The quoted sentences say what the papers report.
Infertility (7 papers, 2016 to 2025). "As reported, PSME4 homozygous males were infertile as reported, and overall heart size was relatively smaller in null mice." (PMID 36015285, 2022). "To analyze the infertility of Psme3/Psme4 dKO male mice, we first investigated the testis histology." (PMID 27003159, 2016). "In this report we showed that the Psme3/Psme4 dKO male mice are completely infertile." (PMID 27003159, 2016). "In this study, we demonstrated that Psme3/Psme4 dKO male mice are completely infertile." (PMID 27003159, 2016). "Whole-body Psme4 knock-out did not result in an overt phenotype, but showed impaired spermatogenesis and infertility." (PMID 37201100, 2023). "In addition, we have previously reported that dKO male mice lacking Psme3 and Psme4 genes are also completely infertile because of sperm suffering from oxidative stress damage." (PMID 37189334, 2023).
male infertility (4 papers, 2016 to 2022). The inability of the male to effect fertilization of an ovum after a specified period of unprotected intercourse. "Taken together, the main reason of Psme3/Psme4 dKO male infertility is due to its inefficient ability to acquire the motility." (PMID 27003159, 2016). "Moreover, the mice lacking PA200/PSME4 do not display a prominent phenotype except for male infertility." (PMID 36009043, 2022).
non-small cell lung carcinoma (3 papers, 2024 to 2025). A group of at least three distinct histological types of lung cancer, including non-small cell squamous cell carcinoma, adenocarcinoma, and large cell carcinoma. "Reduced PSME4 results in an active immunoproteasome, leading to a pro-inflammatory environment in non-small-cell lung carcinoma." (PMID 41462339, 2025).
breast carcinoma (2 papers, 2020 to 2022). "However, mutation events in PSM genes were relatively rare in cancer, which was also observed in the breast cancer validation dataset where only four PSM genes (PSMA4, PSMB7, PSMD3, and PSME4) harbored mutations." (PMID 36123629, 2022).
diabetes (2 papers, 2019 to 2020). "In the group enriched with diabetic patients (6 out of 9 patients), seven proteasome genes (PSME4, PSMA7, PSMB4, PSMB6, PSMC4, PSMD7 and PSMD8) and three genes previously associated with common diabetes (SNX17, PARK7/DJ-1 and ATP5B) were highly expressed." (PMID 32302349, 2020).
hepatocellular carcinoma (2 papers, 2022 to 2024). A malignant tumor that arises from hepatocytes. "In this study, Ge and colleagues show that PA200/PSME4 gene silencing in hepatocellular carcinoma results in reduced mTOR phosphorylation and decreased cell proliferation in vitro." (PMID 36009043, 2022).
lung carcinoma (2 papers, 2024). "PSME4 is an essential component of the proteasome, modulating its activity and diversity in antigen presentation in lung cancer." (PMID 38473427, 2024).
acute leukemia (1 paper, 2016). A clonal (malignant) hematopoietic disorder with an acute onset, affecting the bone marrow and the peripheral blood. "miR-29b, which was recently shown to target the proteasome subunit PSME4 and disrupt the autophagosome pathway in BTZ-resistant MM cells, was not down-regulated in CEM/BTZ cells, indicating non-overlapping profiles in BTZ-resistant acute leukemia and MM cells." (PMID 27542283, 2016).
autoimmune disease (1 paper, 2022). A disorder resulting from loss of function or tissue destruction of an organ or multiple organs, arising from humoral or cellular immune responses of the individual to their own tissue constituents. "In this regard, further studies are warranted to address this hypothesis and determine the relevance of PA200/PSME4 as a potential therapeutic target in cancer and autoimmune diseases." (PMID 36009043, 2022).
interstitial cystitis (1 paper, 2024). A rare chronic debilitating urogenital disease characterized by urinary frequency, urgency, and pelvic pain. "Seven hub genes (SPTBN1, PSME4, CHAC2, ERLEC1, ASB3, STAT5A, and STAT3) were identified as differentially expressed between interstitial cystitis patients and healthy individuals, representing potential therapeutic targets." (PMID 39399486, 2024).
Miscarriage (1 paper, 2022). A pregnancy that ends at a stage in which the fetus is incapable of surviving on its own, defined as the spontaneous loss of a fetus before the 22th week of pregnancy. "The expression of RPA-70, PAK-2, and PSME-4 in missed-miscarriage placental explants that had been treated with GW4869 were significantly higher than in untreated placental explants from missed miscarriage, measured by a semiquantitative analysis." (PMID 36139348, 2022). "Higher levels of cellular senescence-repair proteins, RPA-70, PSME-4, and PAK-2 were seen in placental EVs derived from missed miscarriage, but lower levels of the three proteins were seen in missed-miscarriage placentae, compared with healthy first-trimester placentae." (PMID 36139348, 2022).
mood disorder (1 paper, 2025). A cognitive disorder a disturbance in which the person's mood is hypothesized to be the main underlying feature. "PSME4 also showed differential expression in brain samples from patients with mood disorders." (PMID 41143948, 2025).
ovarian carcinoma (1 paper, 2018). A malignant neoplasm originating from the surface ovarian epithelium. "Enriched proteasome genes, including PSME4 and PSMD14, was exhibited in doxorubicin-derived resistant ovarian cancer cell line, suggesting that this proteasome pathway may be involved in the development of resistance to doxorubicin." (PMID 30001383, 2018).
seminoma (1 paper, 2024). A radiosensitive malignant germ cell tumor found in the testis (especially undescended), and extragonadal sites (anterior mediastinum and pineal gland). "Scanning for somatic mutations in genes involved in antigen presentation and processing, we found one seminoma exhibiting HLA LOH had also acquired a mutation in the proteasome regulator PSME4, which plays a key role in immunoproteasome activity and generating immunopeptidome diversity." (PMID 39461959, 2024).
tuberculosis (1 paper, 2020). A chronic, recurrent infection caused by the bacterium Mycobacterium tuberculosis. "Another marker, PSME4, has been associated with tuberculosis through in vitro and in vivo cultures, and is also related to CD4, IFNβ1, and TGFBI pathways." (PMID 33552042, 2020).
type 1 diabetes (1 paper, 2025). "Among the eight DE genes, PSME4 and NTPCR were shown to be DE in children progressing to type 1 diabetes, in earlier studies, and the promoter region of SLC35E4 was hypermethylated in children progressing to the disease before seroconversion." (PMID 41462339, 2025).
tumor (6 papers, 2019 to 2024). "While the upregulation of PA200/PSME4 in tumor cells can be easily explained by its described function in DNA repair, its reduced expression levels in response to pathogens and/or inflammatory stimuli are enigmatic." (PMID 36009043, 2022). "Previous studies reported that PSME4 plays an indispensable role in the antioxidant response and in maintaining glutamine homeostasis, which is particularly important for long-term survival of tumor cells after radiation exposure." (PMID 34650966, 2021). "The expression level of all PSME genes was significantly correlated with tumor stage for patients with GC, an effect that was especially pronounced for PSME3 and PSME4." (PMID 34650966, 2021). "In the present study, we found that the expression of PSME4 was higher in GC tumor tissues than in non-cancerous tissues." (PMID 34650966, 2021).
cancer (5 papers, 2012 to 2023). A tumor composed of atypical neoplastic, often pleomorphic cells that invade other tissues. "However, the transcriptional studies have revealed specific gene expression patterns under certain circumstances, with PA200/PSME4 being consistently induced in cancer and repressed during infection." (PMID 36009043, 2022). "Proteasome activator subunit 4 (PSME4) is a marker of non-responsiveness to immunotherapy in different cancers." (PMID 37731161, 2023).
infectious disease (1 paper, 2025). A disorder directly resulting from the presence and activity of a microbial, viral, or parasitic agent in humans. "We also identified activation of the PSME4-related infectious diseases response pathway, marked by MYH9 phosphorylation at S1943." (PMID 40842862, 2025).
PSME4 also shares sentences with these, for which no sentence is quoted: neuroblastoma (3 papers); neurodegenerative disease (2); Anxiety (1); benign tumors (1); colon adenocarcinoma (1); dyslipidemia (1); endothelial dysfunction (1); fibrosis (1); gastric cancer (1); glomerulosclerosis (1); HIV-1 infection (1); Huntington disease (1); Hyperglycemia (1); hyperhomocysteinemia (1); idiopathic pulmonary fibrosis (1); infection (1); lung adenocarcinoma (1); lung fibrosis (1); neuropathy (1); Parkinson disease (1); Peri-Implantitis (1); pituitary adenomas (1); stomach adenocarcinoma (1); uterine corpus endometrial carcinoma (1).